STAT2 (signal transducer and activator of transcription 2)
Diseases named in the same sentence as STAT2 in open-access papers (continued):
Sharing a sentence is not in itself a finding about the gene and the disease.
influenza (15 papers, 2017 to 2025). An acute viral infection of the respiratory tract, occurring in isolated cases, in epidemics, or in pandemics; it is caused by serologically different strains of viruses (influenzaviruses) designated A, B, and C, has a 3-day incubation period, and usually lasts for 3 to 10 days. "Despite an exaggerated inflammatory response to influenza infection, we found increased bacterial control and survival in STAT2 deficient mice during influenza-MRSA super-infection compared to controls." (PMID 30337919, 2018). "In this study, we show that STAT2 deficiency improves survival and rescues the impairment of bacterial clearance from the lung otherwise observed during influenza-bacterial super-infection." (PMID 30337919, 2018). "AR STAT2 deficiency is the fifth monogenic etiology of critical influenza to be described." (PMID 36976641, 2023). "Therefore, we hypothesized that STAT2 deficiency would rescue suppression of Type 17 responses during influenza infection." (PMID 30337919, 2018). "This is consistent with previous findings that STAT2 regulates macrophage polarization phenotypes during influenza–bacterial coinfection and in multiple myeloma." (PMID 40873619, 2025). "Together, these results suggest that the STAT2 signaling is involved in suppressing macrophage activation and bacterial control during influenza-bacterial super-infection." (PMID 30337919, 2018). "Consistent with our previous data, we found higher lung bacterial burden in WT BMC mice (WT host/WT BM) than Stat2−/− mice (Stat2−/− host/Stat2−/− BM) during influenza-bacterial super-infection." (PMID 30337919, 2018). "In this study, we investigated the role of STAT2 signaling during influenza and influenza-bacterial super-infection in mice." (PMID 30337919, 2018). "Together our data show a novel role of influenza induced type I IFN-mediated STAT2 signaling in inhibiting bacterial control through suppression of macrophage activity during influenza and influenza/MRSA super-infection." (PMID 30337919, 2018). "Type I interferons such as IFN-α signal through STAT2; STAT2-deficient mice exhibit significantly reduced GzmB expression in lung CD4 T cells following influenza infection, supporting the role of this pathway in generating CD4 CTL in vivo." (PMID 28167943, 2017). "We endogenously deleted two CREs containing expression-modulation variants linked to immune function, rs11624425 and rs80317430, identifying their primary genic targets as ELMSAN1, and PAN2 and STAT2, respectively, three genes differentially expressed during influenza infection." (PMID 34662402, 2022). "The occurrence of life-threatening influenza, which has not previously been reported in this condition, adds STAT2 to the list of monogenetic causes of this phenotype and underscores the critical importance of IFN-I and IFN-III to influenza immunity." (PMID 33679716, 2020). "We recently found a lack of or a small fold viral titer change in STAT1 or STAT2 gene deficient mice infected with influenza infection." (PMID 31159430, 2019). "Also, our recent study has shown that the STAT2 signaling suppress macrophage activation and bacterial clearance during influenza-bacterial super-infection." (PMID 31159430, 2019). "Moreover, it has been previously shown that influenza-infected STAT2–/– B6 mice have increased morbidity and mortality when compared to WT B6 mice." (PMID 31921042, 2019). "Absence of STAT2 was associated with increased accumulation of M1, M2 and M1/M2 co-expressing macrophages during influenza-bacterial super-infection." (PMID 30337919, 2018). "STAT2 and dual function M1/M2 macrophage activation may be a potential target for the treatment or prevention of influenza-bacterial super-infection." (PMID 30337919, 2018).
influenza (continued). "Further, BMC studies showed increased bacterial control in both Stat2−/− BMC and Stat2−/− hematopoietic BMC mice during influenza-bacterial infection, confirming the role of macrophage STAT2 in suppressing bacterial control during influenza-bacterial super-infection." (PMID 30337919, 2018). "We observed increased expression of Stat1, Stat2, Mx1, Oasl2, CCL2, CCL3, CXCL9, and CXCL10 in influenza-infected hearts and lungs when compared to PBS-treated controls." (PMID 38750107, 2024). "Our study further indicated that rosiglitazone treatment decreased downstream signaling agents STAT1, STAT2, and the ISGs Mx1, CXCL9 and CXCL10 during influenza infection." (PMID 31159430, 2019). "Further, increased influenza viral burden in non-hematopoietic Stat2−/− mice indicated a role for stromal STAT2 signaling in inducing ISGs." (PMID 30337919, 2018). "Further, we investigated the role of hematopoietic and non-hematopoietic STAT2 signaling during influenza-bacterial super-infection." (PMID 30337919, 2018). "Together, these data show that in the absence of STAT2 signaling, the increase in Type 1 and Type 2 cytokines during influenza infection creates a pulmonary environment that supports both M1 and M2 macrophage differentiation after super-infection." (PMID 30337919, 2018). "During influenza infection, the binding of T-bet to cytotoxic gene promoters in CD4 T cells is regulated by Blimp-1 expression via a mechanism involving IL-2, type I interferons, and STAT2 signaling." (PMID 28167943, 2017). "The expression of interferon response genes STAT1, STAT2, Mx1, OASL2, ISG15, chemokines CCL2, CCL3, CXCL9 and CXCL10, and the frequency of neutrophils (CD45+CD11b+Ly6G+) and CD4+ T cells (CD45+CD4+) were all significantly increased in influenza-infected mice when compared to vehicle controls." (PMID 38750107, 2024). "These cases revealed the indispensable role of human intrinsic (TLR3, IRF7, IRF9, STAT1, and STAT2 in RECs, in which the virus replicates) and innate (IRF7 in plasmacytoid dendritic cells, in which the virus does not replicate) type I and III IFN immunity in host defense against influenza." (PMID 36112363, 2022). "Further, these data suggest that the absence of stromal cell STAT2 resulted in decreased ISG expression and improved bacterial control in Stat2−/− non-hematopoietic BMC mice (Stat2−/− host/WT BM) during influenza-bacterial super-infection." (PMID 30337919, 2018).
ovarian carcinoma (12 papers, 2017 to 2025). A malignant neoplasm originating from the surface ovarian epithelium. "Signal transducer and activator of transcription 2 has been implicated in the process of multiple cancers, such as ovarian cancer and non-small cell lung cancer." (PMID 34276757, 2021). "In addition, STAT2 is associated with the poor overall survival of ovarian cancer and non-small cell lung cancer." (PMID 34824210, 2021). "STAT2 mRNA level showed a null association with OS amongst all the ovarian cancer patients, HR =1.00 (0.80−1.26), P=0.97, serous ovarian cancer patients, HR =1.04 (0.81−1.34), P=0.74, as well as endometrioid ovarian cancer patients, HR =2.92 (0.30−28.15), P=0.33." (PMID 28536310, 2017). "A recent report indicated that chemoresistance in ovarian cancer is mediated through a FBN1/VEGF/STAT2 signaling axis." (PMID 41440237, 2025). "In previous studies, the Fibrillin-1/VEGFR2/STAT2 signaling axis promoted cisplatin chemoresistance via modulating glycolysis in ovarian cancer cells." (PMID 38184549, 2024). "The Fibrillin-1/VEGFR2/STAT2 signal axis modulated the process of glycolysis and angiogenesis by activating STAT2, which induced cisplatin resistance in ovarian cancer cells." (PMID 36524006, 2022). "According to research, ovarian cancer tissues exhibited higher STAT1 but lowered STAT2-6 expression than normal tissues." (PMID 36524006, 2022). "Studies show that FBN1 regulates glycolysis and angiogenesis through activation of the vascular endothelial growth factor receptor 2 (VEGFR-2)/STAT2 pathway, decreases the sensitivity of ovarian cancer to cisplatin and promotes chemoresistance in ovarian cancer." (PMID 38269088, 2023). "In conclusion, these results suggest that the STAT family plays a significant prognostic role in ovarian carcinoma and individual STATs, except STAT2 and STAT3, may act as favorable prognostic markers in ovarian cancer." (PMID 28536310, 2017). "In summary, our results show that high mRNA expression of all the individual STATs except STAT2 and STAT3 are correlated to a better OS for all the ovarian cancer patients, especially the high level of STAT1 and STAT4 are significantly related to a favorable OS for serous ovarian cancer patients." (PMID 28536310, 2017).
atherosclerosis (9 papers, 2016 to 2025). A disease characterized by the build-up of fatty material and calcium deposition in the arterial wall resulting in partial or complete occlusion of the arterial lumen. "JAK2/STAT2 pathway contributes to homocysteine-accelerated macrophage inflammation, adding to the risk for atherosclerosis." (PMID 36969251, 2023). "Fatty acid binding protein 4 upregulates macrophage inflammation-related interleukin-6 (IL-6) level and regulates lipid metabolism in atherosclerosis induced by activation of the JAK2/STAT2 pathway." (PMID 38835896, 2024). "Therefore, the aim of the present work was to investigate the effect of FABP4 on regulating the JAK2/STAT2 pathway in macrophage inflammation in atherosclerosis." (PMID 34725437, 2022). "In addition to STAT3, other STATs, especially STAT1 and STAT2, also play essential roles in atherosclerosis." (PMID 31588227, 2019). "FABP4 is a well‐known inflammatory regulator involved in various inflammatory diseases such as ischemic stroke, non‐alcoholic steatohepatitis, and atherosclerosis by activating the JNK, NF‐κB, and JAK2/STAT2 signaling pathways in macrophages." (PMID 38884133, 2024). "With regard to the regulatory effect of LDLs on JAK/STAT signaling in human diseases, a microarray analysis indicated that ox-LDLs in atherosclerosis strongly affect the JAK-STAT signaling pathway by acting through STAT1 and STAT2." (PMID 37900720, 2023). "Of all STATs especially STAT1, STAT2, and STAT3 have been recognized as prominent modulators of inflammation, especially in immune and vascular cells during atherosclerosis." (PMID 30283459, 2018). "Although the exact role of STAT2 in atherosclerosis has not been reported, genetic manipulation of the apoF/Stat2 locus supports an important role for STAT2-dependent type I IFN signaling and gene expression in atherosclerosis." (PMID 31588227, 2019).
HCMV infection (8 papers, 2014 to 2022). "STAT1 and STAT2 were also associated with cytomegalovirus infection, in this case, likely through the activation of signaling pathways driven by the autocrine/paracrine secretion of type-I and type-II interferons induced by IRF and NF-κB activation." (PMID 30184180, 2018). "PML was required for accumulation of activated STAT1 and STAT2, interacted with them and HDAC1 and HDAC2, and was associated with ISG promoters after HCMV infection." (PMID 25812002, 2015). "We confirmed known effects of HCMV infection on Jak1, STAT2, and IRF9 and demonstrated that, apart from STAT1, expression of the final effectors in both interferon induction and response pathways were all progressively diminished during infection." (PMID 24906157, 2014). "Phosphorylation levels of IRF9, STAT1, and STAT2 were shown to decrease after HCMV infection." (PMID 34305856, 2021). "Furthermore, after UV-HCMV infection, PML formed a protein complex with STAT1, STAT2, HDAC1, and HDAC2 and associated with ISG promoters." (PMID 25812002, 2015). "Furthermore, we found that during HCMV infection IE1 reduced the association of PML, STAT2, and HDAC1 with ISG promoters." (PMID 25812002, 2015). "Another report showed that human cytomegalovirus infection can activate the type I IFN signaling pathway, which enhances viperin transcription through the STAT1/STAT2/IRF-9 complex termed ISG factor 3 (ISGF3) by binding to the promoter response element ISRE." (PMID 27232627, 2016). "To investigate the mechanism by which PML promotes ISG transcription, we compared levels of IRF3, STAT1, STAT2, and their activated forms in control and PML-knockdown HF cells after UV-HCMV infection." (PMID 25812002, 2015). "Intriguingly, progressive hemophagocytosis after MMR vaccine or cytomegalovirus infections was noted in two of the previously reported cases, as well as in patients with other defects in the type I IFN pathway including STAT1, STAT2, and IFNAR2." (PMID 35091979, 2022). "Since HCMV IE1 inhibits the activation of ISRE-containing promoters by sequestering STAT2 and PML, IE1 expression may be responsible for the suppression of free ISG15 and ISG15 conjugate levels during HCMV infection." (PMID 27564865, 2016). "During HCMV infection, viral IE1 protein interacted with PML, STAT1, STAT2, and HDACs." (PMID 25812002, 2015).
colorectal cancer (7 papers, 2017 to 2025). A primary or metastatic malignant neoplasm that affects the colon or rectum. "Furthermore, several genes included in this list have previously been linked to colorectal cancer (i.e. Id1, Lgals9, Stat2, and Dab2)." (PMID 27129739, 2017). "Although the exact mechanism by which STAT2 promotes colorectal cancer remains to be determined, there is some mechanistic evidence that STAT2 can act outside the canonical IFNAR1-STAT2/STAT1/IRF9 axis via unphosphorylated STAT2." (PMID 41440237, 2025). "In this study, we investigated the relationship between STAT2 expression and patient survival in colorectal cancer and examined the functional role of STAT2 in tumor growth using preclinical tumor models." (PMID 41440237, 2025). "In particular, STAT2 promotes the transcription and expression of acetyl-CoA carboxylase, thus enhancing lipid synthesis in colorectal cancer cells." (PMID 38835896, 2024). "The present study aimed to investigate the role of the transcription factor signal transducer and activator of transcription 2 (STAT2) in colorectal cancer by taking advantage of experimental mouse models and three-dimensional tumoroids." (PMID 38001683, 2023). "Our study investigated the role of the protein STAT2 in colorectal cancer." (PMID 41440237, 2025). "It is conceivable that future therapeutic strategies for colorectal cancer might try to mitigate the actions of STAT2 to improve the treatment outcome in affected patients." (PMID 38001683, 2023). "However, other studies have also shown that STAT2 could promote the tumorigenesis of colorectal cancer (CRC) by upregulating the expression of IL-6 and activating the STAT3 signaling pathway." (PMID 34276757, 2021). "In colorectal cancer (CRC), a malignancy where inflammation and immune modulation are key drivers of disease progression, the role of STAT2 remains poorly defined." (PMID 41440237, 2025). "Our results indicate that STAT2 promotes colorectal cancer by various mechanisms and that anti-cancer drugs could easily kill tumor cells lacking STAT2." (PMID 38001683, 2023).
glioma (7 papers, 2015 to 2022). A benign or malignant brain and spinal cord tumor that arises from glial cells (astrocytes, oligodendrocytes, ependymal cells). "IL10 binds to its corresponding receptor, causing STAT3 phosphorylation through JAK1 and STAT2, which stimulates the proliferation of glioma cells." (PMID 35741689, 2022). "The LFS patient had the highest level of STAT1 and STAT2 expression in an institutional high-grade glioma cohort of 45 patients, further supporting the cancer compendium results." (PMID 34943910, 2021). "Glioma-associated DEGs AKT2, CCL3, STAT2, VEGFC were up-regulated and HIF1A, KRAS, RET, TGFB2 were down-regulated specifically in the dogs." (PMID 29352201, 2018). "Both Stat1 and Stat2 clustered into the glioma-regulated brown module and were around 2.5 fold upregulated." (PMID 25658639, 2015). "In contrast, high STAT2 level in glioma predicts poor patient OS." (PMID 35207629, 2022). "In glioma, the expression of STAT2 was lower in LGG than in GBM." (PMID 34276757, 2021). "The mechanism and function of STAT2 in glioma needs to be further elucidated." (PMID 34276757, 2021). "Western blot analyses demonstrated that, whereas STAT2 and STAT4 showed no prominent or consistent changes in expression, STAT1, STAT3 and STAT5 expression were increased in glioma tissues compared with neighboring non-tumor tissue." (PMID 31530290, 2019).
Immunodeficiency (7 papers, 2019 to 2025). Failure of the immune system to protect the body adequately from infection, due to the absence or insufficiency of some component process or substance. "Moreover, the Open Targets portal revealed that STAT2 was associated with immune system disease and urinary system disease." (PMID 37115061, 2023). "Loss-of-function mutations of JAK3 are associated with severe combined immune deficiency (SCID); similarly, loss-of-function mutations of STAT1 and STAT2 were also found responsible for immunodeficiency, whereas STAT5 deficiency can lead to both immunodeficiency and autoimmunity." (PMID 31443172, 2019). "STAT2 deficiency (STAT2, autosomal recessive inheritance, MIM #600556) has been demonstrated to cause immunodeficiency and sterile meningoencephalitis following childhood vaccinations, associated with hyperfused mitochondria similar to mitochondrial appearances observed in DRP1 deficiency." (PMID 38872485, 2025). "We found multiple genes with ClinVar variants from patients with primary immune deficiencies (for example, IRF9, IRF7, STAT1, STAT2) that are not GWAS-linked genes but are in their network vicinity, providing evidence of the importance of this gene module for these diseases." (PMID 36823319, 2023).